JAK2 (Janus kinase 2)
Diseases named in the same sentence as JAK2 in open-access papers (continued):
Sharing a sentence is not in itself a finding about the gene and the disease.
Thrombocytosis (continued). "Age, parity, history of miscarriage, presence of Janus kinase 2 (JAK2) mutation, history of thrombotic events, treatment of thrombocytosis during pregnancy, and obstetrical outcomes including miscarriage were compared." (PMID 35047285, 2021). "Single case reports have postulated progression to MPN in patients with germline mutations that are known to cause hereditary thrombocytosis, such as development of PV in the presence of JAK2-R867Q." (PMID 33712866, 2021). "The JAK2p.V617F mutation can produce both erythrocytosis in PV and thrombocytosis in ET, while JAK2 exon 12 mutations cause only erythrocytosis." (PMID 33664283, 2021). "This overlap syndrome is characterized by frequent mutations in SF3B1 (90%), that strongly correlate with BM ring sideroblasts, and mutations in JAK2 (40%) that correlate with thrombocytosis." (PMID 33925681, 2021). "In contrast, they are very rare in MDS/MPN-RS-T (<3%), which is characterized by the presence of recurrent JAK2 mutations (35%) that are associated with thrombocytosis and that constitutively activate the JAK/STAT signaling pathway." (PMID 33925681, 2021). "Both MPL and JAK2 mutations have been described to occur in patients with hereditary thrombocytosis and—in somatic form—in MPNs." (PMID 33712866, 2021). "The germline JAK2 mutations were identified both in the pseudokinase (V617I, R564Q S755R) and in the kinase (R867Q, R938Q) domain, giving rise to the thrombocytosis phenotype." (PMID 31618985, 2019). "We retrospectively evaluated 136 cases that underwent JAK2 mutation analysis due to thrombocytosis as a preliminary diagnosis in the hematology clinic." (PMID 29732039, 2018). "The frequency of the JAK2 mutation was reported to be insignificant between men and women with thrombocytosis in a study from Turkey." (PMID 29732039, 2018). "The limitation of our study is that a limited number of cases with thrombocytosis were evaluated in terms of JAK2 mutation, retrospectively." (PMID 29732039, 2018). "In this retrospective study, patients who were admitted to hematology clinic with thrombocytosis between 2013 and 2015 were investigated in terms of the etiological causes of thrombocytosis and the existence of JAK2 mutation." (PMID 29732039, 2018). "In this study, we aimed to investigate the etiologic causes of thrombocytosis and the existence of JAK2 mutation in cases with thrombocytosis, retrospectively." (PMID 29732039, 2018). "JAK2 mutation analysis and bone marrow biopsy are two main procedures to diagnose primary thrombocytosis in adults with persistent thrombocytosis after excluding the causes of secondary thrombocytosis." (PMID 29732039, 2018). "We aimed to investigate the etiologic causes and the existence of Janus kinase 2 mutation (JAK2) in cases with thrombocytosis." (PMID 29732039, 2018). "The recurrent JAK2 V617F mutation occurring at exon 14 of JAK2 was identified in MPNs and refractory sideroblastic anemia with thrombocytosis (RARS-T)." (PMID 28955303, 2017). "The molecular basis of hereditary thrombocytosis is germline mutations affecting the thrombopoietin (TPO)/TPO receptor (MPL)/JAK2 signaling axis." (PMID 28979237, 2017). "By contrast, JAK2-selective inhibitor fedratinib has only minimal inhibitory effects on normal thrombopoiesis but has modest and dose-independent inhibitory effect on thrombocytosis caused by mutant CALR." (PMID 27716741, 2016). "The possibility of sAML transformed from a preexisting undiagnosed MPN was considered and supported by presence of persistent JAK2 V617F mutation, history of long standing gout, and marked thrombocytosis approximately 2 months before his AML presentation." (PMID 27752371, 2016). "In view of the thrombocytosis a JAK2 mutation assay was requested which confirmed a JAK2 V617F mutation, suggesting essential thrombocytosis (ET) as the cause." (PMID 27895669, 2016). "After tumor excision the lasting thrombocytosis induced us to perform bone marrow biopsy and JAK2 mutation research." (PMID 23667719, 2013).
Thrombocytosis (continued). "New potential causes of thrombosis emerged in this patient, including thrombocytosis associated with the JAK2 V617F mutation and the very rare mural thrombosis of the descending aorta." (PMID 21569611, 2011). "Indeed, CALR-mutated patients, as first reported by Klampfl and Nangalia, are younger and characteristically show marked thrombocytosis accompanied by relatively lower hemoglobin and leukocyte counts when compared with JAK2-mutated cases." (PMID 41228192, 2025). "Only three of the five patients with a JAK2 mutation had thrombocytosis or polyglobulia." (PMID 39367633, 2024). "Moreover, the thrombocytosis driven by MPN-associated mutations in Jak2 and hCalr was dependent on intact Mpl-Y599." (PMID 38491305, 2024). "Two patients with combined thrombocytosis were found to have the JAK2 V617F mutation (P15, P16)." (PMID 38886735, 2024). "We may conclude that the large proportion of community-based individuals with thrombocytosis in combination with JAK2/MPL/CALR mutations represented premalignant or underdiagnosed cases of MPN." (PMID 36698617, 2023). "However, in routine practice, many cases of polyglobulia and thrombocytosis lack either the typical MPN mutations in the JAK2, CALR or MPL genes, the histopathological features of MPN, or both." (PMID 37639050, 2023). "Whether this JAK2 mutation drives thrombocytosis through the IDO–Kyn pathway is currently under study." (PMID 37919525, 2023). "Inherited mutations of JAK2 (the most common is JAK2V617F—Janus kinase 2 with valine to phenylalanine substitution on codon 617) are detected in patients with hereditary thrombocytosis, while somatic mutations of the gene link to various phenotypes, including erythrocytosis." (PMID 33671049, 2021). "With the exception of P18 who was treated with hydroxyurea because investigations revealed thrombocytosis with a JAK2 V614F point mutation, second-line agents were initiated because of severity of L-HES disease manifestations and/or requirement for high-dose maintenance OCS therapy." (PMID 32849632, 2020). "JAK2 mutation analysis and bone marrow biopsy are the two main procedures to diagnose primary thrombocytosis in adults with persistent thrombocytosis after excluding the causes of secondary thrombocytosis." (PMID 29732039, 2018). "Finally, the co-existence of additional CALR/MPL or JAK2 exon 14 and exon 12 mutations was routinely excluded in all cases of thrombocytosis or polyglobulia, respectively, that present with a low JAK2V617F AB." (PMID 28422729, 2017). "In view of the thrombocytosis, a JAK2 mutation assay was performed." (PMID 27895669, 2016). "However, she continued to have leukocytosis, thrombocytosis, and a Janus kinase-2 (JAK2+) mutation." (PMID 39439615, 2024). "Indeed, 12.8% of the cases with thrombocytosis carried a JAK2 mutation." (PMID 36698617, 2023). "JAK2 mutation analysis and then a bone marrow biopsy might be a reasonable way to confirm the definite diagnosis after assessment of the characteristics of patients with thrombocytosis and causes of reactive thrombocytosis." (PMID 29732039, 2018). "The marked preoperative thrombocytosis observed in this patient was most likely secondary to tumor-related inflammatory activation, potentially amplified by JAK2 signaling." (PMID 41438978, 2025). "A total of 48.5% of JAK2/MPL/CALR mutant cases with thrombocytosis were diagnosed with a hematological malignancy at follow-up." (PMID 36698617, 2023).
Thrombocytosis (continued). "Mutations in genes associated with MPNs (JAK2, CALR, and MPL) were identified in 32 of 172 (18.6%) individuals with thrombocytosis versus 2 of 175 (1.1%) in their matched controls." (PMID 36698617, 2023). "JAK2 V617F mutations have been reported to occur at a higher frequency in MDS with isolated 5q deletion and cases of MDS/MPN with ring sideroblasts and thrombocytosis." (PMID 36810551, 2023). "Mutations in spliceosome-associated genes were enriched in cases with thrombocytopenia compared with matched controls, whereas MPN-associated mutations (JAK2, CALR, MPL) were enriched in cases with thrombocytosis." (PMID 36698617, 2023). "Antenatal IFN was used in five pregnancies: two with CALR mutation and extreme thrombocytosis (white blood cell (WBC) above 2000 × 109/L), one with JAK2 mutation and prior thrombosis, and two with JAK2 mutation and prior second trimester pregnancy losses." (PMID 36819152, 2023). "Mutations in MPN-associated genes JAK2, CALR and MPL were observed at considerably high frequency in individuals with thrombocytosis." (PMID 36698617, 2023). "Especially mutations in JAK2 (P < 0.001) and CALR (P = 0.003) were enriched in individuals with thrombocytosis." (PMID 36698617, 2023). "SF3B1 and JAK2 mutations are commonly observed together in patients with the distinct overlap syndrome and clinical entity MDS/MPN with ringed sideroblasts and thrombocytosis." (PMID 34193229, 2021). "JAK2, MPL, and CALR mutations define clonal thrombocytosis in about 90% of patients with sustained isolated thrombocytosis." (PMID 34945099, 2021). "STAT3 deletion results in an altered MPN phenotype in JAK2 V617F mice with reduced neutrophilia and enhanced thrombocytosis present." (PMID 34193229, 2021). "We studied 237 JAK2 V617-negative patients who were diagnosed with isolated thrombocytosis and referred to the haematology service." (PMID 34945099, 2021). "A previous study in murine cells suggests that low levels of JAK2 kinase activity favour thrombocytosis whereas high levels favour erythrocytosis, possibly accounting for this inverse relationship." (PMID 32986384, 2020). "The combination of JAK2 V617F and SF3B1 mutations is associated with MDS/MPN with ring sideroblasts and thrombocytosis." (PMID 30573779, 2019). "Sustained activation of JAK2/STAT signaling causes erythrocytosis, leukocytosis and, to a lesser degree, thrombocytosis." (PMID 31395856, 2019). "Genetic alterations of the thrombopoietin (TPO)/MPL/JAK2 axis leading to thrombocytosis and thrombocytopenia." (PMID 28955303, 2017). "Overall, thrombocytosis and thrombocytopenia have been shown to be due to mutations in molecules of the TPO/MPL/JAK2 signaling axis." (PMID 28955303, 2017). "Thrombocytosis is either due to GOF alterations that activate MPL signaling (MPL, JAK2, CALR) or due to LOF mutations of negative regulators of this pathway (CBL, LNK)." (PMID 28955303, 2017). "Overall, the incidence of CALR mutations in wild-type JAK2 and MPL patients was of 44% (15/34) in ET and of 14% (3/21) in persistent thrombocytosis suggestive of MPN." (PMID 25068507, 2014). "While many JAK2 inhibitors are able to achieve normalization of leukocytosis and thrombocytosis, as well as improve symptoms in cancer patients, they are less effective in achieving consistent hematologic remissions and reducing JAK2(V617F) allelic burden." (PMID 24830942, 2014). "Finally, the presence of the JAK2 V617F and history of isolated thrombocytosis brings ET to the top of the differential, although early PMF is not ruled out." (PMID 40104156, 2025). "A total of forty-one pediatric patients with elevated platelet counts diagnosed with ET (nine with CALR driver mutation, eleven with JAK2, thirteen triple-negative, and one dual-negative (TN)) or secondary thrombocytosis (five) were recruited." (PMID 41465385, 2025).
Thrombocytosis (continued). "For example, germline mutations in the JAK2 JH1 and JH2 domains can lead to hereditary thrombocytosis, which mimics sporadic ET and may also involve myelofibrotic transformation." (PMID 40507313, 2025). "The model demonstrated that JAK2 V617F megakaryocytes yield platelets with altered receptor densities and secretory granule content, which directly contributes to the bleeding phenotype despite thrombocytosis." (PMID 40625825, 2025). "The ablation of Stat3 resulted in an altered JAK2 V617F phenotype, with decreased neutrophilia, although thrombocytosis was enhanced, while the ablation of Stat1 actually exacerbated JAK2 V617F-induced erythrocytosis in a mouse model despite reducing the thrombocytosis." (PMID 38254802, 2024). "We can also add that JAK2 mutations, when searched for, was found in a nonnegligible number of patients in our group, sometimes without any thrombocytosis or polyglobulia." (PMID 39367633, 2024). "Co-expression of SF3B1 with DNMT3A, TET2 or ASXL1 promotes myelodysplasia with ring sideroblasts, while acquisition of JAK2 mutations, and less frequently MPL (4%) and SH2B3 (4%) mutations, constitute secondary events that promote thrombocytosis and contribute to the myeloproliferative phenotype." (PMID 33925681, 2021). "We included only JAK2-negative patients as this mutation is the most common in patients with clonal thrombocytosis and has been part of a routine molecular-genetic testing in all patients with suspected clonal thrombocytosis at the time of examination." (PMID 34945099, 2021). "There are not enough studies about the frequency of JAK2 mutation in ET and thrombocytosis cases yet." (PMID 29732039, 2018). "TPO regulates nearly all stages of the megakaryocyte (MK) differentiation, and this explains that numerous diseases characterized by an alteration in MK/platelet production leading to thrombocytopenia or thrombocytosis are due to either acquired or hereditary mutations in MPL, THPO, or JAK2." (PMID 28955303, 2017). "The CALR mutations are present almost exclusively in JAK2-V617F negative patients with ET and PMF, although cases of refractory anaemia with ring sideroblasts associated with thrombocytosis (RARS-T) and PV, in addition to rare cases of JAK2-V617F or BCRABL1 co-positivity have been reported." (PMID 27764253, 2016). "The JAK2 V617F mutation tested negative at diagnosis, but other causes of thrombocytosis were ruled out." (PMID 25525531, 2014). "While screening ENU mutagenized mice for dominant hematopoietic defects, we identified a mouse with thrombocythemia and determined that the mutation resulted in a truncated allele of Jak2 that lacked catalytic activity." (PMID 24086539, 2013). "This suggests that JAK2 V617F does not directly induce an increase in platelets, and that additional mutations or factors are necessary to explain the thrombocytosis in ET patients with JAK2 V617F." (PMID 17183644, 2006). "In murine models of JAK2 deletion in platelets and megakaryocytes (Mk), thrombocytosis via reduced thrombopoietin turnover and expansion of Mk-biased haematopoietic stem cell lineages has been observed and may offer an additional explanation for platelet recovery in this patient." (PMID 40124999, 2025). "Together, these data suggest that interaction between Jak2 and Mpl, dependent on the membrane-proximal intracellular receptor domain and sufficient for basal signalling and platelet production, is insufficient for Jak2-V617F or Calr-del52-driven thrombocytosis." (PMID 38491305, 2024). "We did not observe a significant increase in hsCRP levels in thrombocytosis cases with JAK2-V617F mutations compared with cases without mutant JAK2, but this may likely be explained by the smaller clone sizes in our cohort compared with MPN cases." (PMID 36698617, 2023).
Thrombocytosis (continued). "Apart from individuals with cancer, our findings might be useful in explaining thrombocytosis in individuals without cancer with the JAK2-V617F mutation." (PMID 37919525, 2023). "However, thrombocytosis may occur conversely if the JAK2 expression is downregulated in pro-megakaryocytes, mature megakaryocytes, or platelets." (PMID 35682967, 2022). "Primary hereditary thrombocytosis may be caused by germline mutations within the genes encoding key regulators of thrombopoiesis, i.e., thrombopoietin (THPO) and its receptor c-MPL (MPL) or the receptor’s effector kinase Januskinase2 (JAK2)." (PMID 33712866, 2021). "Here, treatment with tamoxifen in Janus Kinase 2 (JAK2) V617F mutation-induced MPN caused a significant reduction in disease development and eliminated all of the commonly associated phenotypes of the disease including erythrocytosis, thrombocytosis and leukocytosis." (PMID 32276421, 2020). "Since cases with thrombocytosis were assessed only in terms of the frequency of JAK-2 mutation in that study and the frequencies were found to be different from those in other studies that assessed the frequency of JAK-2 mutation in cases with BCR‐ABL‐negative CMDs." (PMID 29732039, 2018). "The lack of thrombocytosis suggests that additional events may be required for JAK2 V617F to cause ET, but qualitative platelet abnormalities induced by JAK2 V617F may contribute to the hemostatic complications of PV." (PMID 17183644, 2006). "However, with Jak2 deletion, degradation may be compromised, leading to increased availability of Tpo in the BM and subsequent expansion of megakaryocyte progenitors, resulting in thrombocytosis." (PMID 40825505, 2025). "However, the presence of reactional thrombocytosis does not formally exclude the hypothesis of underlying ET hence the importance of detecting the three driver mutations (JAK2, MPL and CALR) in persistent thrombocytosis." (PMID 36980287, 2023). "This binding is followed by the constitutive ligand independent activation of Janus kinase 2 and signal transducer and activator of transcription 5 (JAK2/STAT5) signal pathway which results in dysregulated megakaryopoiesis and the occurrence of thrombocytosis." (PMID 33806036, 2021). "Regarding platelets, it is not well understood why Fedratinib had the paradoxical effect in reducing thrombocytosis in the PTMF model, as expected from a JAK2 inhibitor, but reducing thrombopenia observed in the PPMF model." (PMID 26176817, 2015). "CALR was studied in wild-type JAK2/MPL patients including 34 ET, 21 persistent thrombocytosis suggestive of MPN and 98 suspected secondary thrombocytosis." (PMID 25068507, 2014). "Among JAK2/MPL-negative samples a total of 15 ET and 4 persistent thrombocytosis suggestive of MPN showed a clear distinctive pattern of the melting and difference curve plot compared with those of the wild-type." (PMID 25068507, 2014). "Vice versa, increased coupling of Jak2-R1063H with TpoR promotes mild thrombocytosis without elevated circulating Tpo." (PMID 40841769, 2025). "As described in previous mouse models, we found that the excess megakaryopoiesis and thrombocytosis driven by expression of Jak2-V617F or Calr-del52 were ablated in the absence of Mpl." (PMID 38491305, 2024). "While the molecular findings with a JAK2 R564L point mutation suggested an overlap MDS/MPN syndrome, the presence of markedly increased ring sideroblasts in the absence of thrombocytosis argued against the diagnosis of an MDS/MPN-RS-T." (PMID 36810551, 2023). "In the newly diagnosed JAK-2 positive cases with abnormal blood counts, all had an isolated thrombocytosis, without erythrocyte count abnormality." (PMID 35493844, 2022). "In cases of familial MPN exhibiting hereditary thrombocytosis and triple-negative MPN, it is proposed that the inherited JAK2 mutations signal through TPOR rather than EPOR." (PMID 31618985, 2019).